IFNG (interferon gamma)
Diseases named in the same sentence as IFNG in open-access papers (continued):
Sharing a sentence is not in itself a finding about the gene and the disease.
tumor (continued). "However, the role of IFNG in tumor cells is rarely reported." (PMID 39945555, 2025). "By secreting cytokines such as TNF-α, interleukin-12 (IL-12), and interferon-gamma (IFN-γ), N1 neutrophils facilitate the polarization and activation of cytotoxic T cells and NK cells, creating a pro-inflammatory microenvironment that promotes tumor immune surveillance." (PMID 40486595, 2025). "A small fraction of tumor cells recognized by T cells can trigger widespread IFNγ sensing, with bystander tumor cells also exhibiting significant expression of IFNγ-induced Katushka fluorescent protein, indicating that IFNγ signals can propagate over distances exceeding 800 μm within tumor tissue." (PMID 40995371, 2025). "Additionally, IFNG boosted tumor angiogenesis via HMGB1 pathways, which could be mitigated by HMGB1 inhibition." (PMID 39945555, 2025). "While IFNγ is known to elicit potent antitumor immunity through T cell activation and Th1 polarization, IFNγ induction of PD-L1 expression may alternatively serve to attenuate local tumor immunity, providing the rationale for the combinatorial approach with ICI to enhance antitumor immunity." (PMID 40515479, 2025). "Moreover, we found that the important interferon molecule IFNG was highly expressed specifically in HER2 + IBC tumour-infiltrating B cells and antibody-secreting cells, suggesting a possible interfering role of IFNG in the normal activation and differentiation of B cells." (PMID 40624675, 2025). "Analysis of effector activity of these tumor-infiltrating CD4+ T cells revealed that T-bet-deficient CD4+ T cells had markedly impaired functionality in both saline and M002 treatment groups, as the IFNγ+TNFα+ population and the expression of GzmB were significantly reduced." (PMID 39885128, 2025). "In addition, the GSEA analysis results suggest that high expression of SOX10 may exert a pro tumor effect by inhibiting the interferon gamma (IFN-γ) response and JAK/STAT signaling pathway." (PMID 40342816, 2025). "Interestingly, CXCL6 and other ARGs also showed negative correlations with checkpoints like VEGFB, KIR2DL1, LAG3, CTLA4, PDCD1, and IFNG, indicating they may promote immune surveillance and anti-tumor responses." (PMID 40943183, 2025). "Additionally, HMGB1 released during the ICD of tumor cells promotes IFNG secretion by CD8+ T cells." (PMID 39945555, 2025). "As CD8+ T cells were important for limiting IFNγRKO tumour growth, and the production of IFNγ enables the inflammatory myeloid landscape responsible for IFNγRKO tumour control, we hypothesised that CD8+ T cells regulate the myeloid landscape in IFNγ-insensitive tumours." (PMID 39746898, 2025). "Nanoparticulated IFNγ could concentrate on the ablation site and play a long-term regulatory role in the tumor immune microenvironment after iRFA treatment through slow release, while avoiding toxic and side effects of IFNγ on surrounding normal tissues and the whole body." (PMID 39776793, 2025). "However, local release of pro-inflammatory IFNγ also increases PD-L1 expression on tumor cells." (PMID 40102596, 2025). "Additionally, pulmonary host B cells were found to enhance IFNγ production and facilitate NK cell killing of tumor cells, suggesting that effector B cells may have a protective role against cancer." (PMID 41019045, 2025). "The low levels of TNFα and IFNγ induced by both treatments might be ascribed to tumor debulking." (PMID 41471045, 2025). "Collectively, these results indicate that the glycosyltransferase MGAT1 acts as a crucial negative regulator of CD8+ T cells in immune-cold TNBC, whose accumulation could contribute to tumor immune evasion through suppressing cytotoxic IFNγ-secreting CD8+ T cell function." (PMID 40229283, 2025).
tumor (continued). "To investigate whether the superior therapeutic efficacy observed in Trp2.Combo-treated mice compared to Ifna.Il12 was associated with generation of tumor-specific CD8+ T cells, we performed an IFNγ ELISPOT assay on CD8+ T cells purified from the spleens of treated mice." (PMID 40216735, 2025). "Concurrently, IFNγ can upregulate Acyl-CoA Synthetase Long Chain Family Member 4 expression through STAT1/IRF1 signaling, facilitating the integration of tumor microenvironment-associated arachidonic acid into phospholipids, inducing ferroptosis in tumor cells." (PMID 40136510, 2025). "Moreover, BMDMs exhibited the strongest antigen cross-presentation ability during co-incubation with tumor cell lysates and Nano-IFNγ/Zole, which was reflected in the up-regulation of MHC-I molecules loaded with tumor-specific antigen epitope peptides(SIINFEKL)." (PMID 39776793, 2025). "Our results suggest that a strong depletion of Tregs combined to prominent expansion of effector T cells could lead to excessive IFNγ-dependent responses in the tumor microenvironment, which may explain the unrestrained pruning of tumor endothelial cells in this setting." (PMID 40460830, 2025). "As interferon gamma facilitates tumor infiltration of CD8+ T cells and is ultimately a marker of CD8+ T cell activity, we next investigated whether CGB7 expression affects CD8+ T cell infiltration using immune phenotype classification data for tumor samples from the IMVigor 210 cohort." (PMID 40501795, 2025). "Hence, ICB may enhance the ability of MHC-II– mdTAM_4 to respond to both IFNγ and IgG-opsonised tumour cells/antigens." (PMID 40523200, 2025). "Additionally, more immunogenic tumor conditions, marked by IFNγ production, may contribute to Treg destabilization." (PMID 40164596, 2025). "Notably, SFV vectors, particularly when combined with IFNγ, appear to suppress GM-CSF and other broad-spectrum tumour-related pathways while inducing a pro-inflammatory state in macrophages, highlighting the complexity and multifaceted nature of TAM regulation." (PMID 40547518, 2025). "While the effect of IFNγ alone may be sufficient it could be particularly valuable in poorly infiltrated tumors, where the spatial and temporal distribution of IFNγ secreted by activated CD8+ T cells within the tumor microenvironment is limited, resulting in areas with low IFNγ concentration." (PMID 39258533, 2025). "Besides its immunomodulatory effects on tumor-infiltrating immune cells like macrophages, dendritic cells, and T cells, IFNγ can exert its antitumor activity by directly inhibiting the proliferation of tumor cells and endothelial cells, or by promoting tumoral cell death." (PMID 40645933, 2025). "The expression and mutation profiles of IFNG, KEAP1, and PHKG2 may serve as indicators of the tumor mutational burden (TMB) in OV, indicating their potential utility as predictive biomarkers for tumor response and prognosis." (PMID 40744688, 2025). "However, IFNγ diffuses in the tumor microenvironment and can reach considerable distance from its initial site of release, which may explain why TA-HEVs are also affected by this cytokine." (PMID 40460830, 2025). "Results of IVIS imaging indicated that compared to Nano-IFNγ/Zole in solution, preferable amount of zoledronate in the Nano-IFNγ/Zole in gel could retain in tumor lesions for more than 15 days, although a little amount of released zoledronate distributed to bones due to its bone-targeting property." (PMID 39776793, 2025). "IFNγ-producing tumor-specific CD8+ T cells could also sensitize HCC cells to TKI." (PMID 40645933, 2025). "Additionally, tumor cells escape IFNγ-induced immune elimination by downregulating the expression of signaling molecules, switching to alternative signaling pathways that are associated with tumor promotion and survival, or undergoing G0/G1 cell cycle arrest and entering a quiescent state." (PMID 38831317, 2024).
tumor (continued). "An increased number of activated cytotoxic CD8+ T-cells could also lead to an increased effect of CD8+ T-cell produced IFNγ and finally important for the reduction of tumour growth in infected animals, as we find that neutralization of IFNγ was able to reverse this effect." (PMID 38271469, 2024). "Additionally, IFNγ producing CD8 + T cells are known mediators of anti-tumour immunity." (PMID 39242821, 2024). "Consequently, it is possible that this increased interferon-gamma production from TILs may lead to an upregulation of PD-L1 expression in the tumor tissue, which allows cancer cells to evade immune detection." (PMID 38990441, 2024). "Indeed, other studies have found that MAP kinase activation could promote anti‐tumour macrophages similar to IFNγ‐activated M1‐type macrophages." (PMID 39330930, 2024). "In this study, we improved the virus-induced tumor immunogenicity of recombinant Semliki Forest virus (rSFV)-based replicon particles by encoding immunogenic cytokines such as C-X-C motif chemokine ligand 10 (CXCL10), FMS-like tyrosine kinase 3 ligand (Flt3L), or interferon-gamma (IFN-ƴ)." (PMID 38425844, 2024). "2DG as a glycolysis inhibitor could also suppress anti-tumor T cell responses as glycolysis supports the fast proliferation of activated T cells and is crucial for several effector functions, particularly the secretion of interferon gamma (IFN-γ)." (PMID 39408714, 2024). "The type 1 immune cytokine IFNγ promotes macrophage polarisation towards the anti-tumour proinflammatory IL-12-producing phenotype, while stimulation by the type 2 cytokines IL-4 and IL-13 results in polarisation towards the tumour-promoting alternatively activated phenotype." (PMID 38745765, 2024). "The mitogen-activated protein kinase (MAPK) pathway, the PTEN-PI3K-AKT signaling pathway, the WNT/b-catenin signaling pathway, interferon-gamma (IFNγ) signaling pathways, and lack of tumor antigen expression have been identified to be associated with tumor immune escape." (PMID 39669365, 2024). "Furthermore, some studies indicate that the available concentration of IFNγ might dictate its tumor-supportive or opposing role, with low levels of the cytokine inducing metastasis and tumorsphere formation, while high-dose infusion leads to tumor regression." (PMID 38831317, 2024). "In addition to tumor cells, IFNγ signaling culminates in immune cell activation." (PMID 38167862, 2024). "Moreover, interferon gamma has been demonstrated to upregulate a multitude of checkpoint inhibitors, including programmed death ligands 1 and 2, on the surface of macrophages, dendritic cells, and tumor cells." (PMID 39596210, 2024). "In addition, IFNγ has a proapoptotic effect on cancer cells, limiting tumor growth in vivo." (PMID 38831317, 2024). "However, further experimental validation that directly evaluates the impact of IFITM3 loss in an immunocompetent mouse model can shed further light on the direct impact of IFNγ-IFITM3 axis mediated from the tumor immune microenvironment on therapeutic resistance in AML." (PMID 38418901, 2024). "However, IFNγ exposure can also induce immunosuppressive phenotypes, such as regulatory T cells (Tregs) and exhausted T cells, ultimately leading to immune evasion and tumor growth." (PMID 39294470, 2024). "For example, Ifngr2 (encodes the receptor for type 1 cytokine interferon-γ (IFNγ)), was enriched in cLTMR neurons, suggesting these neurons preferentially responded to IFNγ-producing cells, such as CD8+ T cells and NK cells, which are mediators of anti-viral and anti-tumor immunity." (PMID 38806708, 2024). "Additionally, IFNG plays a significant role in tumor immune angiogenesis." (PMID 39687628, 2024). "Tumor tissue based next-generation sequencing revealed the potential associations between several biomarkers and pathological response, including tumor neoantigen burden score, 18-gene expression profile score, CD8 + T cells, M1/M2 macrophages ratio and interferon-gamma expression level." (PMID 38853265, 2024).
tumor (continued). "Notably, NAD+ metabolism drives IFNγ-induced PD-L1 expression to lead to tumor immune evasion." (PMID 38254798, 2024). "In contrast, low-dose interferon gamma might lead to tumor progression." (PMID 38706595, 2024). "Indeed, recent studies have shown that IFNγ also has important tumor-promoting functions that are less well understood and include the ability of IFNγ to induce the expression of immune checkpoints and T-cell exhaustion and increase cancer cell proliferation and migration." (PMID 39123403, 2024). "Because the loss of IFNγ expression was confined to the Foxp3+ Treg population, we hypothesize that IFNγ production by fragile and instable Tregs may contribute to increased infiltration of the tumor by CD8+ T cells in FS120m-treated mice, resulting in enhanced antitumor immunity." (PMID 38995700, 2024). "The production of IFNγ is not only a major factor in the antiviral and bacterial activity of NK cells but also a factor that may promote the apoptosis and cytolysis of target tumor cells." (PMID 39457710, 2024). "Moreover, when used in conjunction with anti-PD1, LD4172 reshapes the tumor immune microenvironment by enhancing the infiltration of dendritic cells and IFNγ+ T cells, as well as by promoting the secretion of immunostimulatory cytokines, leading to antitumor effects." (PMID 39681571, 2024). "However, some studies have shown that IFNγ in the tumor microenvironment (TME) may promote cancer immunosurveillance in the presence of NK cells." (PMID 39457710, 2024). "Moreover, in an in vivo mouse tumor model, β-glucan treatment enhanced the secretion of IFNγ." (PMID 39337403, 2024). "However, Tregs are important suppressors in the tumor environment, while IFNγ prevents the neogeneration of Tregs through reactive oxygen species (ROS)-mediated apoptosis, and counteracts IL-10 and Transforming growth factor-β (TGF-β) signaling-mediated inhibition." (PMID 38827732, 2024). "In addition to direct antitumor activity, CD4+ CAR T cells may induce IFNγ-dependent remote cytolytic tumor cell death and promote host immune cell activation, further complementing phagocytosis-potentiating therapeutic approaches like the one presented here." (PMID 39521782, 2024). "Therefore, we hypothesized that LXR agonist-induced apoptosis of tumor cells might be related to IFNγ expression." (PMID 38630355, 2024). "Currently, it is unknown whether the upregulation of PD-L1 in the patient’s tumor referenced in this study is associated with the upregulation of MHC-I; however, we demonstrated increased levels of Her-2/neu-specific IFNγ production in the patient in a phase Ib trial." (PMID 38203458, 2023). "Importantly, PARP14 silencing in IFNγ pre-treated tumours reversed these alterations in the TME." (PMID 37752135, 2023). "Therefore, lactate may modulate the GBM immunosuppressive microenvironment through targeting immunocytes and modulate tumor response to IFNG." (PMID 37122693, 2023). "Therefore, IFNγ has anti-tumorigenic effects, which significantly suppress tumor growth." (PMID 37190141, 2023). "In B16OVA, substantial concentrations of IL-12 could be measured in the interstitial fluid of tumors injected with the mRNA encoding IL-12 and IL-12-taFv1, and as a result, increased concentrations of IFNγ were also measurable in such recovered tumor interstitial fluid." (PMID 37650116, 2023). "Metabolic reprogramming is one of the hallmarks of tumors, and it not only plays a crucial role in tumorigenesis and tumor signaling but also has a broader significance in antitumor effects through the release of metabolism-related factors (e.g., lactate, arginine, tryptophan, IFNγ, and PD-L1)." (PMID 36854755, 2023).
tumor (continued). "Notably, the transfer of CART19-28z SNX9 KO was accompanied with increased serum levels of anti-tumor effector molecules IFNγ, Perforin, and Granulysin, while we detected a decrease in IL10 and IL6 (human CCL5 could not be detected in the serum)." (PMID 36732507, 2023). "Specific tumor cells may also alter their intracellular signaling pathways in response to T-cell-redirecting therapy, as one study showed that disrupted interferon-gamma signaling in HER2-positive tumor cells conferred resistance to killing by BiTE/CAR-redirected T cells." (PMID 37760519, 2023). "In addition, IFNγ-driven increased expression of chemokines in tumors of Dox-treated mice, such as CCL2, CCL3, CCL5, and CXCL16 has been associated with enhanced recruitment of CD8+ T cells to tumors and reduced tumor progression." (PMID 37478172, 2023). "Moreover, neutralizing IFNγ was found to reduce the anti-tumour effects." (PMID 37056922, 2023). "Moreover, by detecting the proportion of CD8+ IFNγ+ T cells in the spleen and tumor of the two groups of tumor-bearing mice, we found that the ability of CD8+ T cells derived from BAFF KO tumor bearing mice to secrete IFNγ was significantly increased compared with WT tumor bearing mice." (PMID 35725835, 2023). "However, in that report, during LCMV infection the loss of SHP2 resulted in enhanced expansion (almost 3 fold) of virus-specific effector CD8+ T cells and in a tumor model the ability of PD-1 blockade to enhance the percentage of total and IFNγ positive intra-tumoral CD8+ T cells was SHP2-dependent." (PMID 36960049, 2023). "Quantitative PCR (qPCR) confirmed a significant increase of mRNA expression for the chemokine ligands Cxcl10 and Cxcl11, supporting our hypothesis that PARP14 inhibition enhances IFNγ signalling in tumour cells and upregulates immune cell infiltration into tumours." (PMID 37752135, 2023). "Although cytokines like Interferon alpha (IFN-α) and Interferon gamma (IFN-γ) theoretically bolster the cytotoxicity of T cells against tumors, their therapeutic efficacy in clinical trials has been limited, indicating that cytokine function can also be dysregulated in the tumor microenvironment." (PMID 37928544, 2023). "Induction of PD-L1 expression can be prevented by disrupting the tumor cell response to IFNγ signaling, rendering PD-1-PD-L1 blocking ineffective; however, this strategy represents a mechanism of resistance not only to the immune checkpoint, but also to anti-tumor immunity." (PMID 37144580, 2023). "Thus, while serum IFNγ has been recently shown to inversely correlate with tumor progression and metastasis, the data presented here show a broader picture of the mechanics through which IFNγ influences outcomes, by regulation of the immune cell types in the tumor microenvironment." (PMID 36675137, 2023). "However, when anti-IFNγ antibody was administered simultaneously with cisplatin, it impaired the beneficial effects of chemotherapy, which was consistent with the observation that IFNγ might be involved in anti-tumour immunity during chemotherapy." (PMID 37056922, 2023). "For example, IFNγ has seemingly opposing effects on tumor cell viability in vitro and in vivo: the cytostatic effects of IFNγ largely inhibit tumor cell growth in vitro, whereas in vivo, the induction of PD-L1 by IFNγ provides a strong, cytoprotective effect that overcomes those inhibitory effects." (PMID 37398651, 2023). "As such, insensitivity to IFNγ might be predicted to benefit tumour cells in the context of ICBT." (PMID 37752135, 2023). "Thus, IFNγ induction of Qa-1b on tumor cells prior to CAR-T exposure may be necessary to witness the effect of Qa-1b inhibition on CAR-T anti-tumor activity." (PMID 38052854, 2023).